PIK3CA (phosphatidylinositol-4,5-bisphosphate 3-kinase catalytic subunit alpha)
Diseases named in the same sentence as PIK3CA in open-access papers (continued):
Sharing a sentence is not in itself a finding about the gene and the disease.
breast cancer (continued). "Among the autopsy samples of cases with primary breast cancer, we found mutations in EGFR in one liver and one lymph node metastases, and a mutation in PIK3CA in all the samples from one case, and in a liver metastasis from another." (PMID 20604919, 2010). "We can thus suggest a link between gain-of-function mutation in PIK3CA, up-regulation of WNT5A and favorable outcome in breast cancer." (PMID 21209903, 2010). "Our findings in serous ovarian carcinoma, and the previous results from studies of breast cancer and glioblastoma, are in contrast to ovarian carcinoma of endometrioid type, and endometrial cancer, where PTEN mutations and PIK3CA mutations frequently co-exist." (PMID 18208621, 2008). "Two PIK3CA mutants observed in breast cancer (E545K and H1047R) were also tested in the MCF-10A immortalized breast epithelial cell line." (PMID 19384426, 2007). "We found a high frequency of these somatic alterations of PIK3CA gene in a large number of primary breast cancers." (PMID 16168105, 2005). "We also treated several breast cancer cells with the PIK3CA inhibitor LY294002 and compared the apoptosis status in cells with and without PIK3CA mutation." (PMID 16168105, 2005). "To determine the PIK3CA gene copy number, we performed real-time quantitative PCR on 12 breast cancer cell lines, 92 primary tumors, and 33 normal controls." (PMID 16168105, 2005). "The phase III INAVO120 trial demonstrated that inavolisib in combination with palbociclib and fulvestrant significantly improved survival outcomes compared with palbociclib plus fulvestrant in PIK3CA-mutated, HR+/HER2- breast cancer patients with endocrine resistance." (PMID 41496420, 2026). "PIK3CA mutations are associated with specific clinicopathological features but do not significantly impact prognosis in breast cancer patients." (PMID 40472482, 2025). "Data from CAPItello-291 have led to the regulatory approval of capivasertib–fulvestrant in patients with HR-positive/HER2-negative advanced breast cancer and one or more tumor biomarker alterations (PIK3CA, AKT1 or PTEN) in several countries, including in Japan and the US." (PMID 39379782, 2025). "Mutations such as PIK3CA H1047R and the overexpression of markers like YAP/TAZ are associated with oligometastatic breast cancer (OMBC) and may predict better responses to local therapy." (PMID 40723288, 2025). "However, we observed a significant difference between PIK3CA wild-type and mutant breast cancer patients (p = 0.03)." (PMID 40740245, 2025). "Based on the CAPItello-291 phase III trial results, capivasertib in combination with fulvestrant has been approved for patients with hormone receptor-positive/human epidermal growth factor receptor 2-negative advanced breast cancer harboring one or more PIK3CA, AKT1, and/or PTEN alterations." (PMID 40597213, 2025). "The maturation of the RNA cap involving guanosine N-7 methylation, catalyzsed by the HsRNMT (RNA guanine-7 methyltransferase (HsRNMT)-RAM (RNA guanine-N7 methyltransferase activating subunit (RAM) complex, is currently under investigation as a novel strategy to combat PIK3CA -mutant breast cancer." (PMID 39869500, 2025). "Although PIK3CA mutations are present in all breast cancer subtypes, Estrogen Receptor (ER) positive and HER2 negative patients have a higher mutation frequency." (PMID 40472482, 2025). "Furthermore, we investigated the potential of ncRNAs as anticancer agents in PIK3CA-mutant breast cancer." (PMID 40142329, 2025). "While alpelisib shows a clear clinical benefit in PIK3CA-mutant breast cancer, the complexity of signaling networks in glioma may require broader or combination-based strategies." (PMID 40508087, 2025).
breast cancer (continued). "This may offer a mechanistic underpinning for the phenotypic heterogeneity found in PIK3CA-driven breast cancer models as well as in benign but highly debilitating human PROS disorders." (PMID 39706867, 2025). "A total of 3795 patients were included in the analysis, of which 982 had colorectal cancer with 421 KRAS‐positive cases and 36 NRAS‐positive cases, 1246 had breast cancer with 410 PIK3CA‐positive cases, and 1567 had non‐small cell lung cancer with 300 EGFR‐positive cases." (PMID 40056420, 2025). "As exosome-targeted nanomedicine presents promising opportunities for cancer therapy, developing nanodrugs that target MDSC-derived exosomes may offer a breakthrough in treating PIK3CA-mutant breast cancer." (PMID 41281644, 2025). "Additionally, we discovered trans correlations between specific gene alterations (FANCA, HRAS, PIK3CA, MAP2K1, JAK2) and the expression of 22 proteins, suggesting potential molecular mechanisms underlying breast cancer development and progression." (PMID 39844043, 2025). "Among TNBC stage I-III breast cancers with early (N = 134) and late (N = 66) recurrence, the most frequent alteration was PIK3CA (20.2% vs 33.3%), followed by BRCA1/2 (6.0% vs 9.1%), PD-L1 amplification (2.2% vs 3.0%), PALB2 (1.5% vs 0%), and ESR1 (0% vs 1.5%)." (PMID 40421962, 2025). "It suggested that lncRNAs may serve as potential therapeutic targets in PIK3CA mutant breast cancer." (PMID 40142329, 2025). "The phase III INAVO120 trial showed that in patients with PIK3CA-mutated, HR+ HER2- advanced breast cancers, treatment with inavolisib (plus palbociclib and fulvestrant) led to a significant overall survival benefit, although adverse effects were more frequent with inavolisib." (PMID 40806432, 2025). "Here, we utilize experimental models of breast cancer, both dependent and independent of PIK3CA mutation." (PMID 41408399, 2025). "On the other hand, PIK3CA mutations, which are overwhelmingly prevalent in breast cancer, are not biased towards young ages." (PMID 41279109, 2025). "In HR+/HER2- breast cancer, 8.7% (87 of 995) of hotspot alterations associated with an on-label matched therapy were detected at a VAF <5%, comprising alterations in AKT1, ESR1, PIK3CA, and PTEN." (PMID 40711866, 2025). "Performance summary analysis in the breast cancer Random Forest (PTP53 vs PIK3CA) classifiera." (PMID 41342203, 2025). "Kras is not commonly mutated in human breast cancer, but Pik3ca is the most commonly mutated breast cancer proto-oncogenes." (PMID 41000773, 2025). "The status of PIK3CA may influence the efficacy of targeted therapy and endocrine therapy in breast cancer patients." (PMID 40472482, 2025). "A meta-analysis of 1929 breast cancer cases identified PIK3CA mutations as independent negative prognostic factors, with a hazard ratio of 1.67 (95% CI: 1.15–2.43; p = 0.007) and an associated reduction in median OS by 8.4 months." (PMID 40149275, 2025). "Since the PI3K pathway is frequently hyperactivated in breast cancer typified by a high frequency of PIK3CA mutations, we analyzed the effect of USP10 depletion in the breast cancer cell lines MCF7 (PIK3CA-E545K) and T47D (PIK3CA-H1047R), which both harbor activating mutations in PIK3CA." (PMID 40991650, 2025). "This review aimed to investigate novel treatments for PIK3CA-mutant breast cancer." (PMID 40142329, 2025). "Activating PIK3CA lesions were shown to have a prognostic value in breast cancer, however, their role may differ in early- and late-stage tumors." (PMID 40507317, 2025).
breast cancer (continued). "In human epidermal growth factor receptor 2-positive (HER2+) breast cancer patients undergoing HER2-targeted treatment, patients with PIK3CA mutations showed lower progression-free survival (PFS) than those with wild-type PIK3CA (hazard ratio (HR) 4.602, 95% CI 2.057–10.514, p < 0.001)." (PMID 40142329, 2025). "Additionally, PIK3CA and AKT1 mutations, as well as the loss of PTEN, contribute to the estrogen‐independent growth of breast cancer cells." (PMID 40206206, 2025). "In contrast, PIK3CA mutations showed a weak association with circPVT1 expression in the entire breast cancer cohort but not in TNBC subtype." (PMID 40114244, 2025). "Unlike inavolisib, which is only indicated for patients with PIK3CA-mutated breast cancer, gedatolisib has demonstrated activity in patients with or without PIK3CA mutations." (PMID 40711480, 2025). "Finally, this study examined noncoding RNAs as potential therapeutic targets for PIK3CA-mutant breast cancer." (PMID 40142329, 2025). "For taselisib, studies have shown that in patients with HER2‐negative, hormone receptor‐positive advanced breast cancer, regardless of PIK3CA mutation status, the combination of taselisib and fulvestrant has clinical activity." (PMID 40292733, 2025). "Additionally, for advanced breast cancer patients with PIK3CA, AKT1, or PTEN alterations who have previously received CDK4/6i, capivasertib in combination with fulvestrant presents a viable treatment option." (PMID 40206206, 2025). "In the present study, we assessed the molecular and cellular effects of gedatolisib in combination with fulvestrant, with and without palbociclib, in ER+ breast cancer cell lines with or without PIK3CA/PTEN mutations." (PMID 40565304, 2025). "Notably, AKT1, ERBB2 (HER2), CDK4, and CCNE1 are significantly amplified in tumor samples while PIK3CA displays the lower expression level in breast cancer." (PMID 40725120, 2025). "Moreover, the expression levels of SESN3, CRIP1, DPP4 and PIK3CA were significantly upregulated in breast cancer samples compared to control samples." (PMID 41357233, 2025). "They suggested that ncRNAs may serve as potential therapeutic targets or agents for PIK3CA mutant breast cancer by modulating the expression levels of PIK3CA genes." (PMID 40142329, 2025). "In addition to Fulvestrant, Capivasertib was added to the treatment regimen in patients with HR+ advanced breast cancer with alterations in PIK3CA, AKT1, or PTEN." (PMID 40943615, 2025). "PIK3CA mutations are also implicated in acquired resistance to anti-EGFR therapy in metastatic colorectal cancer patients, similar to the resistance to trastuzumab seen in breast cancer." (PMID 40508087, 2025). "Several clinical trials have been conducted on PIK3CA-mutant breast cancer." (PMID 40142329, 2025). "Similarly, clinical trials in PIK3CA-mutant breast cancer have demonstrated that the combination of the PIK3CA-selective inhibitor alpelisib and estrogen receptor (ER) degrader fulvesterant improves radiographic progression-free survival." (PMID 39919177, 2025).
breast cancer (continued). "Among HER2 + stage I-III (N = 95) and stage IV (N = 78) breast cancers, the most frequent alterations, other than HER2 amplification, were PIK3CA mutations (26% vs 41.0%), followed by BRCA1/2 (6.3% vs 6.4%), ESR1 (1.1% vs 3.9%) mutations, and PD-L1 amplification (1.1% vs 0%)." (PMID 40421962, 2025). "The PIK3CA gene encodes the p110α catalytic subunit of PI3K, and PIK3CA mutations are reported in various human cancers, occurring in approximately 15% of cases, with higher prevalence in gastrointestinal and breast cancers." (PMID 40576713, 2025). "Amplification of the PIK3CA gene locus and other rare genetic alterations, such as PIK3CB amplification or PIK3R1 inactivating mutations, have been identified, further highlighting the complexity of this pathway’s involvement in breast cancer." (PMID 39850811, 2024). "Yet, the hotspot mutations of PIK3CA consistently occur at roughly a 2:1 (H1047R:E545K) ratio regardless of breast cancer subtype." (PMID 38802751, 2024). "Among 40 recurrent driver alterations described in breast cancer, only HER2 amplification, germline BRCA1/2 mutations, and PIK3CA mutations were given level 1A evidence as molecular targets whereas NTRK fusions and microsatellite instability (MSI) were ranked as 1C evidence." (PMID 38869741, 2024). "Overall, 21 breast cancer specimens containing pathology-validated tumor and adipose tissues were analyzed and results were compared using uni- and multivariate statistics on normal, WT and PIK3CA mutant ductal carcinomas." (PMID 39294437, 2024). "Clusters in which breast cancer was exclusive or dominant contained PIK3CA or GATA3 genes." (PMID 39040139, 2024). "Mutant RAS- and PIK3CA-driven breast cancers distinctly affect the function of skeletal muscle." (PMID 38651826, 2024). "We demonstrated that the combination synergistically decreases the survival of HR+ breast cancer cells harboring PIK3CA mutations or PTEN loss and elicits robust anti-tumor activity in PIK3CA-mutant PDX models resistant to alpelisib and/or palbociclib combined with endocrine therapy." (PMID 39409880, 2024). "Notably, in colon, ovarian, cervical, and breast cancers, patients with multiple PIK3CA mutations exhibited a distinct pattern of PTEN mutation co‐occurrence compared with those with a single PIK3CA mutation." (PMID 39054873, 2024). "Many pathogenic gene mutations common to breast cancer, such as Pten, Brca2, Atm, Cdh1, Chek2, Nf1, Arid1a, Pik3ca, and Esr1, revealed no alterations between NT2.5 and NT2.5-LM." (PMID 38717519, 2024). "Therefore, the phase II BYLieve trial evaluated patients with PIK3CA-mutated, HR-positive, HER2-negative advanced breast cancer after progression on a CDK4/6 inhibitor plus an AI and alpelisib continued to show efficacy in combination with fulvestrant." (PMID 38396649, 2024). "Moreover, triplet therapy with palbociclib, taselisib, and fulvestrant has been reported to have a positive effect in patients with heavily pretreated PIK3CA-mutantER-positive (ER+)/HER2- advanced breast cancer." (PMID 39711963, 2024).
breast cancer (continued). "Desmedt and colleagues identified alterations in one of three key genes of the PI3K pathway: PIK3CA, PTEN, and AKT1, in 50% of ILC breast cancer cases, each more frequently mutated in ER-positive/HER2-negative ILC breast cancer than in ER-positive/HER2-negative invasive ductal breast cancer tumours." (PMID 38534931, 2024). "Therefore, antitumor activity was observed in patients with PIK3CA mutant breast cancer (3 partial response and 3 stable disease of a total of 6 patients)." (PMID 39070139, 2024). "Although these drug studies have demonstrated a therapeutic effect on endocrine-resistant breast cancer, alpelisib is only suitable for patients with PIK3CA mutations and has not yet been approved in China." (PMID 39544302, 2024). "The Phase 3 placebo-controlled CAPltello-291 trial reported an improvement in progression-free survival with the addition of the AKT inhibitor, capivasertib to fulvestrant in patients with ER+ advanced breast cancer, irrespective of PIK3CA mutation status." (PMID 39251829, 2024). "PIK3CA, the most frequently mutated oncogene in luminal breast cancer, can affect the PAM signaling pathway regardless of receptor status, while 4% of cases have mutations of AKT-1 and PTEN." (PMID 38504785, 2024). "Although multiple compounds have been developed, at present, there are just three inhibitors approved to target this pathway in patients with advanced ER-positive, HER2-negative breast cancer: everolimus (mTOR inhibitor), alpelisib (PIK3CA inhibitor), and capivasertib (AKT inhibitor)." (PMID 38927964, 2024). "FDA-approved therapies specific to breast cancer include Olaparib, which has demonstrated clinical efficacy for patients with ATM, BRCA1/2, and CHEK2 mutations, as well as alpelisib for patients with PIK3CA mutations." (PMID 38927753, 2024). "Correlative biomarker analysis of the BOLERO2 trial assessing the efficacy of everolimus in combination with exemestane in HR+/HER2- refractory advanced breast cancers showed that PFS was independent of underlying genetic alteration of PIK3CA." (PMID 39322687, 2024). "This could be attributed to the fact that PIK3CA and RUNX1 mutations are commonly observed in luminal-type breast cancer; in the intrinsic subtype, CDH1-altered ILC exhibited a higher proportion of luminal-type cases." (PMID 39201647, 2024). "Since in 0% GF PI 3-kinase activity appears to control the cell cycle in lines harboring the PIK3CA H1047R mutation, we studied cell cycling in the presence of 1 or 5 μM BYL719, which is the specific PI3-kinase α inhibitor approved for breast cancer treatment under the name of Alpelisib." (PMID 38786098, 2024). "Although research in this area is still evolving, preclinical data suggest that combining specific PI3K inhibitors with existing anti-HER2 therapies may enhance their efficacy and help to avoid resistance in cases of PIK3CA-mutant HER2+ advanced breast cancer." (PMID 39769140, 2024). "While the PIK3CA mutation was not elucidated during her breast cancer evaluation earlier in life, now that it has been identified, she can be screened and treated for thromboembolic sequelae more aggressively moving forward." (PMID 39354592, 2024). "Consequently, capivasertib has become the first FDA-approved AKT inhibitor for use in HR-positive and HER2-negative breast cancer patients with one or more PIK3CA/AKT1/PTEN alterations." (PMID 38791529, 2024). "Furthermore, we explore the intricate signaling pathways modulated by PIK3CA, with a particular focus on their influence on tumor tropism in breast cancer, emphasizing TNBC." (PMID 39369580, 2024). "PIK3CA alterations have been reported in 24–40% of patients with breast cancer." (PMID 38229073, 2024).